LTBP1 (latent transforming growth factor beta binding protein 1)
Diseases named in the same sentence as LTBP1 in open-access papers (continued):
Sharing a sentence is not in itself a finding about the gene and the disease.
Anxiety (1 paper, 2020). Intense feelings of nervousness, tension, or panic often arise in response to interpersonal stresses. "This encouraged us to further evaluate the function of LTBP1 and possibly find a potential bridge built by LTBP1 that could link depressive/anxiety and GBM." (PMID 33059753, 2020).
Aortic root aneurysm (1 paper, 2022). An abnormal localized widening (dilatation) of the aortic root. "Human relevance is supported by recent studies implicating genetic lesions in LTBP3 and, potentially, LTBP1 as heritable causes of aortic root aneurysm." (PMID 35098309, 2022).
asthma (1 paper, 2021). "The LTBP1 was the most consistently associated gene in a favorable ICS response among asthma patients." (PMID 33923891, 2021).
CADASIL (1 paper, 2014). "Nonetheless, our findings suggest an LTBP-1-mediated sequestration of LAP into Notch3-ECD aggregates and point to an involvement of the TGF-β pathway in CADASIL pathogenesis." (PMID 25190493, 2014).
CARASIL (1 paper, 2021). CARASIL is a hereditary cerebral small vessel disease characterized by early-onset gait disturbances, premature scalp alopecia, ischemic stroke, acute mid to lower back pain and progressive cognitive disturbances leading to severe dementia. "Impaired TGF-β signaling, due to a lack of LTBP-1 processing by HtrA1, is thought to promote the pathogenesis of CARASIL, but the underlying molecular mechanisms are not fully understood." (PMID 34946804, 2021).
choriocarcinoma (1 paper, 2021). An aggressive malignant tumor arising from trophoblastic cells.
chronic hepatitis C (1 paper, 2016). "LTBP1 was previously found to be up-regulated in liver tissue from patients with chronic hepatitis C." (PMID 26998606, 2016).
Cirrhosis (1 paper, 2022). A chronic disorder of the liver in which liver tissue becomes scarred and is partially replaced by regenerative nodules and fibrotic tissue resulting in loss of liver function. "We found them to be upregulated in cirrhosis represented by the upregulation of PGDFRB, TGFB1 (TGF‐β1), TGFB1I1 (TGF‐β1 induced transcript 1 protein), TGFBI (TGF‐β induced protein ig‐h3), LTBP1, LTBP2, LTBP4, and ENG (transmembrane accessory receptor for TGF‐beta signaling)." (PMID 35579278, 2022).
complication (1 paper, 2017). Any disease or disorder that occurs during the course of, or because of, another disease, treatment, or procedure. "The greater angiogenic potential of T2DM–BMMSCs secretome may reflect the interactive actions of multiple bioactive mediators (including IGF‐1, LTBP1 and LTBP2) which may alter the functions of endothelial cells, key players in diabetic vascular complications." (PMID 27641937, 2017).
esophageal cancer (1 paper, 2020). A primary or metastatic malignant neoplasm involving the esophagus. "There was a significant positive correlation between LTBP1 and FN1 expression in esophageal carcinoma (r = 0.6, p < 0.001, spearman correlation analysis)." (PMID 32216815, 2020).
fibrosis (1 paper, 2016). the formation of excess fibrous connective tissue in an organ or tissue in a reparative or reactive process. "Notably, large amounts of two members of LTBPs (LTBP1 and LTBP4) were found deposited in the ECM of patients with stage F3 fibrosis." (PMID 26998606, 2016).
heart failure (1 paper, 2023). Inability of the heart to pump blood at an adequate rate to meet tissue metabolic requirements. "Although ADAMTS enzymes are considered to have a narrower substrate repertoire than other ECM-proteolytic enzymes, fibronectin and LTBP1 are not the only substrates of potential relevance in heart failure." (PMID 37216909, 2023).
Hernia (1 paper, 2025). "Moreover, both NCAM1 and LTBP1 were consistently expressed in all patient samples, providing evidence of their involvement in the hernia development." (PMID 39903526, 2025).
Hyperglycemia (1 paper, 2025). An increased concentration of glucose in the blood. "In our experiments, the expression of ITGB6 and LTBP1 increased in a time-dependent manner under high-glucose conditions, reinforcing their potential roles in hyperglycemia-induced injury." (PMID 41244197, 2025).
infarcts (1 paper, 2025). "Notably, LTBP1 and CRIP1, along with C1QC and PRSS23 (linked to WMH and infarcts) and CEMIP and ELN (associated with WMH and microbleeds), showed strong co-localization with ThioS- positive vascular amyloid deposits, but not with parenchymal plaques." (PMID 41282800, 2025).
Infertility (1 paper, 2026). "Our findings, for the first time, demonstrate a significant association between the expression of LTBP1 and TGF-βR1 and abnormal sperm morphology, supporting their consideration as novel exploratory biomarkers for further investigation in infertility, especially in TER men." (PMID 41686770, 2026).
keloid (1 paper, 2018). An irregularly shaped, elevated mark on the skin caused by deposits of excessive amounts of collagen during wound healing. "HtrA1 may facilitate keloid pathogenesis through the activation of TGF-β1 mediated by LTBP-1 cleavage." (PMID 29695130, 2018).
leiomyoma (1 paper, 2007). A well-circumscribed benign smooth muscle neoplasm characterized by the presence of spindle cells with cigar-shaped nuclei, interlacing fascicles, and a whorled pattern. "LTBPs consist of LTBP-1 to LTBP-4 with LTBP-1 and -2 expression reported in leiomyomas." (PMID 17716379, 2007).
lymphoma (1 paper, 2023). A malignant (clonal) proliferation of B- lymphocytes or T- lymphocytes which involves the lymph nodes, bone marrow and/or extranodal sites. "Blocking the interaction between TGF-β and LTBP1 can impede the activity of natural killer/T cells by deactivating the TGF-β/Smad and p38MAPK signaling pathways, consequently impacting the advancement of lymphoma." (PMID 37895143, 2023).
medulloblastoma (1 paper, 2023). A malignant, invasive embryonal neoplasm arising from the cerebellum. "Of these seven genes (LTBP1, MAP1A, MBNL2, LGALS1, PNRC1, DAB2, and PLAAT3), only one, LGALS1, had been researched previously in relation to medulloblastoma, where it is up-regulated in MBSHH patients and activated by the SHH signalling pathway." (PMID 36831428, 2023).
mesothelioma (1 paper, 2014). A usually malignant and aggressive neoplasm of the mesothelium which is often associated with exposure to asbestos. "Furthermore LTBP1 may play a key role in the pathogenesis of mesothelioma via regulation of TGFβ activation in tumor tissue." (PMID 24708840, 2014).
metastatic tumors (1 paper, 2022). "Treatment with carboplatin not only arrested the LTBP1-related metastasis in vivo but also downregulated the TGF-β1 signaling in metastatic tumors, and the mechanism was found to be regulated by LTBP1 expression." (PMID 36629522, 2022).
neuroendocrine tumors of (1 paper, 2013). "LTBP1 is downregulated in a variety of human epithelial neoplasms of liver, ovaries and neuroendocrine tumors of the digestive system." (PMID 23741501, 2013). "In neoplasms of liver, ovaries and neuroendocrine tumors of the digestive system expression of LTBP1 is reduced." (PMID 23741501, 2013).
NK/T cell lymphoma (1 paper, 2023). "Elevated LTBP1 levels in NK/T cell lymphoma (NKTCL) result in heightened TGFβ-1 secretion and release within the TME." (PMID 37895143, 2023).
Ovarian cyst (1 paper, 2024). The presence of one or more cysts of the ovary. "Adult female mice lacking Ltbp1 exhibit impaired fertility characterized by ovarian cyst formation and reduced estrogen and progesterone levels." (PMID 39570927, 2024).
pseudoexfoliation syndrome (1 paper, 2024). "Two studies reported LTBP1 and LTBP2 upregulation in the anterior segment of human tissues with pseudoexfoliation syndrome." (PMID 38928268, 2024).
pulpitis (1 paper, 2023). Inflammation of the dental pulp. "In addition, we discovered that the knockdown of latent transforming growth factor beta binding protein 1 (LTBP1) remarkably suppressed the immunoregulation ability of pericytes in vitro and compromised their in vivo regenerative potential in pulpitis." (PMID 38137420, 2023). "Moreover, we tried to determine whether the knockdown of LTBP1 could influence the in vivo regenerative potential of pericytes in the pulpitis model." (PMID 38137420, 2023).
Sepsis (1 paper, 2023). Sepsis is defined as life-threatening organ dysfunction caused by a dysregulated host response to infection. "Interestingly, we found that LTBP1 was hypomethylated in sepsis, which encodes an important protein for the TGF-β1 activity regulation." (PMID 37077915, 2023).
tuberculous pleurisy (1 paper, 2023). "It has already been demonstrated that overexpressed LTBP-1 is associated with several fibrotic conditions, such as allograft arteriosclerosis and tuberculous pleurisy." (PMID 37894778, 2023).
tumor (31 papers, 2003 to 2025). "We identified all cysteine mutations showing a plasma cell tumor phenotype in each potential binding partner (LTBP1–4, FBN1–3, LRC32/33, and SELE)." (PMID 36214621, 2022). "Dysregulation of Latent Growth Factor beta Binding Protein (LTBP1) has been identified in asbestos-related lung tumors and was associated with DNA copy number alterations and tumor-associated miRNAs." (PMID 24708840, 2014). "The tumor microenvironment may also be influenced by the regulation of tumor-associated macrophages (through LTBP-1 and POSTN)." (PMID 40143207, 2025). "This led to the loss of an essential DNA modification, 5hmC, and the down-regulation of tumor-suppressive genes, including latent transforming growth factor beta-binding protein 1 (LTBP1)." (PMID 40520993, 2025). "Most strikingly, our analysis revealed a seven-gene drug-tolerant signature in all four drug-tolerant cell lines, irrespective of chemotherapeutic treatment, parental cell line and tumour subgroup—LTBP1, MAP1A, MBNL2, LGALS1, PNRC1, DAB2 and PLAAT3." (PMID 36831428, 2023). "The mRNA expression and protein level of latent transforming growth factor beta binding protein 1 (LTBP1) were detected in tumor tissues and paracancerous tissues from in-house samples." (PMID 36629522, 2022). "BMP1, CD109, and LTBP1 showed a gradual and clear increase of expression from the control tissues to the metastatic tissues, with preferential cytoplasmic staining in the tumour tissue, being more intense in metastasis." (PMID 36134447, 2022). "LTBP1 can be inhibited by other enzymes, leading to the maintenance of tumor cell growth under hypoxic conditions." (PMID 35568859, 2022). "LTBP1 displayed an upregulated status in MSI-H patients with worsening tumor status, including the Grade 3 (P =0.334), stage III/IV (P =0.245), and T3 + T4 stage (P = 0.236)." (PMID 33316777, 2020). "In LTBP1 positive cases, the expression of LTBP1 was mostly located in tumor parenchymal margin, while E-cadherin was mainly expressed in tumor center, suggesting that LTBP1 promoted ESCC cells to acquire mesenchymal phenotype in tumor parenchymal margin." (PMID 32216815, 2020). "Indeed, while LTBP1 was mainly expressed in tumor tissues, FN1 was highly expressed in fibroblasts of the stroma, suggesting a potential correlation between the overexpression of the two genes, which synergistically act to induce EMT." (PMID 37947594, 2023). "The increase of tumor metastasis induced by LTBP1 knockdown can be arrested by carboplatin." (PMID 36629522, 2022). "And among these genes, LTBP1 was differentially expressed between tumor and normal tissue." (PMID 33059753, 2020). "Thus, we supposed that LTBP1 facilitated TGFβ-induced ESCC cells to acquire mesenchymal phenotype in tumor parenchymal margin." (PMID 32216815, 2020). "We then conducted a tail vein metastasis assay to study whether LTBP1 plays an important role in tumor metastasis in vivo." (PMID 32216815, 2020). "In addition, the regulation of tumor-associated macrophages (LTBP-1 and POSTN) could make the tumor microenvironment more favorable for the spread of cancer cells." (PMID 40143207, 2025). "Meanwhile, the expression of MYH9, FN1, LTBP1, CALR and AKAP12 is effective in discriminating HR-NB from LR-NB patients, indicating that these non-invasive biomarkers may be used to detect patients at risk of developing aggressive tumor phenotypes." (PMID 37947594, 2023). "Interestingly, we found that LTBP1 was overexpressed in tumor parenchymal margin." (PMID 32216815, 2020). "Eight genes (CDH23, HARS2, LLGL2, LTBP1, MAP6D1, MIPOL1, SCYL3, ZNF418) showed some degree of promoter methylation in at least one tumour, but only MIPOL1 exhibited probable homozygous methylation in more than one sample." (PMID 39794353, 2025). "Functionally, the inhibition of LTBP1 by PTPS leads to impaired secretion of TGF-β, thereby sustaining tumor cell growth under hypoxic conditions." (PMID 39457539, 2024).
tumor (continued). "Osteoclasts are capable of cleaving LTBP1, which is subsequently involved in the release of TGF-β from the bone matrix during bone resorption and will then fuel tumor growth in the bone niche." (PMID 35243294, 2022). "Most mice injected with HELA CON cells had metastasis signals in the lungs, and in the LTBP1 shRNA group, the GFP signal was increased due to the accumulation of tumor cells." (PMID 36629522, 2022). "Immunohistochemical staining was performed to visualise the expression of BMP1, CD109, LTBP1, PSAP, and NPC2 in human control colonic tissue, primary tumour, and liver metastasis." (PMID 36134447, 2022). "Using TCGA normal data only, LTBP1 was the only gene that had significantly differential expression between normal and GBM tumor tissue." (PMID 33059753, 2020). "Western blot results showed that FN1(11/12),LTBP1(11/12), PLOD2(11/12), RCN3(10/12), THBS1(11/12) were increased in tumor tissues (Paired-samples t-test, p < 0.05), indicating that the screening results of TMT technology were credible." (PMID 32216815, 2020). "In LTBP1 highly expressed ESCC tissues, the expression of FN1 was also very high in the stroma surrounding tumor nests." (PMID 32216815, 2020). "Thus, inhibition of LTBP1 may be a potential pathway to suppress EMT of tumor cells." (PMID 32216815, 2020). "Likewise, TGF-beta binding (TB) domain superfamily (LTBP1, LTBP2, FBN2; p = 4.76e-06) was over-represented in upregulated tumor ECM proteins." (PMID 35340765, 2022). "In fact, we were able to detect five upregulated proteins in the normal mucosa adjacent to the tumor, namely laminin subunit alpha-4 (LAMA4), elastin microfibril interfacer 1 (EMILIN1), LTBP1 and fibrinogen beta chain (FGB), as well as proteoglycan versican core protein (VCAN)." (PMID 35340765, 2022). "LTBP1 and FN1 had different expression patterns in tumor cells and fibroblasts." (PMID 32216815, 2020). "The lack of correspondence between exosomes and tumor tissues for VASP, LGALS3BP, MYH9 and LTBP1 could be due to the fact that these vesicles are loaded through active mechanisms." (PMID 37947594, 2023).
cancer (21 papers, 2017 to 2025). A tumor composed of atypical neoplastic, often pleomorphic cells that invade other tissues. "A study also reported that the suppression of LTBP1 can attenuate cancer-associated fibroblast (CAF) transformation and inhibit FN1 in ESCC." (PMID 34456964, 2021). "Functional experiments have shown that the knockdown of LTBP1 inhibited the invasive and migratory abilities of ESCC cells and decreased the epithelial-mesenchymal transition and cancer-associated fibroblast transformation, suggesting an oncogenic role of LTBP1 in ESCC progression." (PMID 41019096, 2025). "Of the top down-regulated genes, PLAGL1, CTH and VIM are positively correlated with HNSCC, while increased expression of RMRP, SULT1 and LTBP1 has been recorded in other cancers." (PMID 31827722, 2019). "Together, these results led us to conclude that LTBP1 has a reduced expression in cancer tissue." (PMID 36629522, 2022). "In the lungs, DKK1 also reduced the latent transforming growth factor-beta binding protein-1 (LTBP1)-mediated transforming growth factor-beta (TGF-β) secretion of cancer cells by inhibiting Wnt/Ca2+-calmodulin-dependent protein kinase II) (CaMKII)-Nuclear factor-κb (NF-κB) signaling." (PMID 34093545, 2021). "LTBP1 was mainly observed in cancer cells while FN1 was mainly observed in the surrounding stroma." (PMID 32216815, 2020). "Our above studies implied that LTBP1 involved in cancer progression via TGFβ-induced EMT." (PMID 32216815, 2020). "The BMP1 substrate LTBP1 was expressed at similar levels in all but only one cancer patient." (PMID 29720137, 2018). "However, the exact functions of LTBP1 seem paradoxical in various cancer types." (PMID 32216815, 2020). "In scRNAseq analysis, LTBP1 and LTBP2 were expressed dominantly in CAFs alone, while LTBP4 was strongly expressed in CAFs, in addition to pericytes and cancer cells." (PMID 40075643, 2025). "Secondly, LTBP-1 targets latent TGF-β1 to the ECM by interacting with different proteins including fibronectin and fibrillin, generating deposits of latent TGF-β1 accessible for cell-mediated activation and regulating cancer cell proliferation and immunity." (PMID 33059753, 2020). "Moreover, flow cytometry cell cycle assay revealed a higher proportion of S and G2-M phases in LTBP1 high expression group, which was reported by many other researches to be an important feature of EMT in many type of cancers, including GBM." (PMID 33059753, 2020). "In the cancer group, ARIDS, HEBP1, LTBP1, and PLVAP were identified as candidate genes." (PMID 31747953, 2019). "Although TTC27 is absent in three cancer gene databases, the breakpoints disrupt MSigDB and COSMIC CGC genes BIRC6 and LTBP1, resulting in a LTBP1-BIRC6 gene fusion of unclear effect." (PMID 38947031, 2024).
LTBP1 also shares sentences with these, for which no sentence is quoted: Alzheimer disease (2 papers); colorectal cancer (2); metastatic cancer (2); Stroke (2); abdominal aortic aneurysm (1); anemia (1); arterial diseases (1); ascending aortic dilation (1); atherosclerosis (1); basal cell carcinoma (1); Blindness (1); brain tumors (1); breast (1); Cerebellar atrophy (1); chronic kidney disease (1); coronary artery disease (1); diabetic kidney disease (1); diabetic retinopathy (1); hepatocellular carcinoma (1); Intellectual disability (1); ischemic stroke (1); lung carcinoma (1); microphthalmia (1); movement disorder (1); Obesity (1); ovarian carcinoma (1); pancreatic cancer (1); plasma cell tumor (1); pregnancy (1); psychosis (1).
A further 4 diseases each share a sentence with LTBP1 in 1 paper.